RUNX1 (RUNX family transcription factor 1)
Diseases named in the same sentence as RUNX1 in open-access papers (continued):
Sharing a sentence is not in itself a finding about the gene and the disease.
COVID-19 (6 papers, 2021 to 2023). A disease caused by infection with severe acute respiratory syndrome coronavirus 2. "Our results suggest that COVID-19 is causing upregulation of IgG production leading to activation of classical complement through C1S, which produces a downregulation of RUNX1 and TYK2 signaling, that blocks T-cell maturation and mutes Th1/Th17 immune response, respectively." (PMID 34899680, 2021). "Of note, up to 78% of these genes exhibit binding sites for this factor, highlighting the important role of RUNX1 in the physiopathology of COVID-19." (PMID 36943669, 2023). "Overall, dysregulation of these pathways was common throughout the convalescent COVID-19 patient population, emphasizing a “core signature,” with upregulation of the RUNX1 pathway, which regulates the expression of many dysregulated genes." (PMID 36943669, 2023). "In association with hemostasis and platelet function, we also observed a highly enriched Reactome pathway “RUNX1 regulates genes involved in megakaryocyte differentiation and platelet function” in our COVID-19 specific signature." (PMID 35991542, 2022). "The results indicated that both PPARγ and PPARα are downregulated, while SOX17 and RUNX1 gets upregulated in COVID-19 patients." (PMID 34407143, 2021). "A recent study suggested that RUNX1 inhibitor may be beneficial as both a treatment and preventive therapy for COVID-19." (PMID 35073995, 2022). "Interestingly, the COVID-19 specific signature was also highly enriched with genes from the Reactome pathway “RUNX1 regulates genes involved in megakaryocyte differentiation and platelet function” (R-HSA-8936459, FDR < 10−5), showing consistent COVID-19 specific upregulation." (PMID 35991542, 2022). "The two TFs were RUNX1 in the TRNs of healthy B cells, basophil/mast cells, dendritic cells, macrophage/monocyte cells, NK cells and COVID-19 patients’ AT2 cells and B cells and FOS in the TRNs of healthy ciliated and endothelial cells and COVID-19 patients’ ciliated cells and NK cells." (PMID 35458567, 2022). "From 11 healthy cell-type TRNs and 8 COVID-19 cell-type TRNs, we identified 8 unique central TFs, FOXP1, RUNX1, FOS, SMAD3, JUN, NFKB1, PPARG, and STAT3." (PMID 35458567, 2022).
diabetes (6 papers, 2016 to 2022). "Associated cardiovascular diseases include diabetes (PDLIM5, HDAC4, and TLE1), cardiac development (PDLIM5) and myocardial aging (CASP12), hypertension (PFKP and TAB2), and intracerebral and intraventricular bleeding (RUNX1) and stroke (AXIN2)." (PMID 36620623, 2022). "Well-established tumor-associated pathways including WNT signaling, RUNX1 signaling, and NOTCH signaling were associated with GCG expression in COADREAD, suggesting an interplay with deregulated GCG signaling, such as in altered glucose homeostasis of diabetes mellitus which is a known risk factor." (PMID 35340411, 2022). "To test for RUNX1 involvement in human disease, we interrogated gene expression of macrophages obtained from carotid atherosclerotic plaques of patients with or without diabetes (Excel File I in the Data Supplement)." (PMID 34255973, 2021). "EVA1C is a Slit receptor involved in Robo-mediated axonal guidance, OLIG2 regulates spinal cord oligodendrocyte and motor neuron development, IFNAR1 is an interferon receptor with no role in the initiation or progression of diabetes and RUNX1 is involved in haematopoiesis." (PMID 27195491, 2016).
Hyperglycemia (6 papers, 2021 to 2025). An increased concentration of glucose in the blood. "Runx1, which mediates trained immunity produced by hyperglycemia, is implicated by the pattern of open chromatin." (PMID 36895942, 2023). "The transcription factor runt-related transcription factor 1 (Runx1) is key in hyperglycemia-induced trained immunity." (PMID 41028520, 2025). "Further analysis revealed involvement of the Runt-related transcription factor 1 (Runx1) in translating hyperglycaemia into persistent proatherogenic changes of the bone marrow." (PMID 36795085, 2024). "These in vitro signs of trained immunity brought on by hyperglycemia were eliminated by pharmacological suppression of Runx1." (PMID 36895942, 2023). "Pharmacological inhibition of RUNX1 removed these manifestations of hyperglycemia-induced trained immunity in vitro." (PMID 34255973, 2021). "The targeted intervention against RUNX1 provides further evidence of the involvement of RUNX1 in the downstream effects of hyperglycemia-induced trained immunity in macrophages." (PMID 34255973, 2021). "In addition to cholesterol, hyperglycemia also elicits trained immunity of BM-derived macrophages and their precursors, although this occurs via epigenetic activation of the Runt-related transcription factor 1 (Runx1), a crucial transcription factor that regulates the leukemogenic expansion of HSCs." (PMID 38327649, 2023).
osteosarcoma (6 papers, 2010 to 2025). A usually aggressive malignant bone-forming mesenchymal neoplasm, predominantly affecting adolescents and young adults. "Runx1 is an important transcription factor that regulates the fate of osteosarcoma stem cells, maintaining the undifferentiated state of osteosarcoma stem cells by collaborating with the Notch pathway." (PMID 40989695, 2025). "Runx1 and Ikzf1 have been shown to be targets of mirn23a miRNAs in hematopoietic cells, and Satb1 was shown to be a direct target in osteosarcoma cells." (PMID 28704388, 2017).
prostate adenocarcinoma (6 papers, 2016 to 2024). "To expand on this observation, we performed CRISPR-Cas9 mediated RUNX1-KO in another T-ALL cell line (Jurkat), AML (HL60) and prostate adenocarcinoma (DU145) cell lines, contexts where increased RUNX1 expression is associated with disease progression." (PMID 37213235, 2023). "In prostate adenocarcinoma (PARD), however, RUNX1 expression was shown to be decreased." (PMID 35522574, 2022). "RUNX1 and RUNX2 had similar cancer expression profiles, with overexpression in most cancer types and downregulation in prostate adenocarcinoma (PRAD)." (PMID 39822248, 2024). "RUNX1, RUNX2, and RUNX3 were all highly correlated with immune cell infiltration in the HNSC, KIRC, LGG, liver hepatocellular carcinoma (LIHC), and prostate adenocarcinoma (PRAD)." (PMID 36321611, 2023).
Stroke (6 papers, 2012 to 2024). Sudden impairment of blood flow to a part of the brain due to occlusion or rupture of an artery to the brain. "Genetic evidence linking these factors to vascular disease includes a variant in the RUNX1 locus associated with stroke (rs116262092-A) and colocalization of a STAT3 VSMC eQTL with a CAD GWAS signal." (PMID 39215134, 2024). "Microglia/macrophage-specific responses to stroke included the persistent upregulation of the genes encoding the microglia activating factors Cebpa, Cebpd, the mitogenic factor Runx1 and the Ctse protease, required for chemotaxis and cell adhesion in macrophages, in both age groups." (PMID 23251410, 2012). "RUNX1 is involved in angiogenesis, and its expression level is much higher in young rats after stroke than in old rats." (PMID 37323662, 2023). "Mechanistically, circPDS5B recruits hnRNPL to enhance the stability of Runx1 and ZNF24 mRNA, promoting the expression of Runx1 and ZNF24 and inhibiting the transcription of VEGFA, thereby enhancing angiogenesis after stroke." (PMID 38203348, 2023).
atherosclerosis (5 papers, 2022 to 2024). A disease characterized by the build-up of fatty material and calcium deposition in the arterial wall resulting in partial or complete occlusion of the arterial lumen. "CEBPD and RUNX1 were identified as the key regulators for both atherosclerosis-associated cell states despite the higher expression of Cebpd in Vcam1+ SMCs and Runx1 in Col2a1+ SMCs." (PMID 37060905, 2023). "Accordingly, we investigated the therapeutic effects of the RUNX1 inhibitor, Ro5-3335, in established atherosclerosis mouse models." (PMID 39113793, 2024). "RUNX1 has long been considered as a potential therapeutic target in atherosclerosis." (PMID 38368442, 2024). "RUNX1, which may function as an important TF in the pathogenesis of patients with RA complicated with atherosclerosis, was predicted to participate in the regulation of the two hub genes CSF1R and ITGB2." (PMID 35304503, 2022). "Therefore, we hypothesized that RUNX1 is epigenetically regulated by exercise in atherosclerosis." (PMID 39113793, 2024). "The transcription factors RUNX1, GATA1, STAT3, NFκB, and PPAR have been widely reported to play key roles in the pathophysiology of platelet hyper-reactivity, thrombosis, and atherosclerosis." (PMID 36969155, 2023).
B-cell lymphomas (5 papers, 2010 to 2025).
bone marrow failure syndrome (5 papers, 2016 to 2024). "Mono-allelic RUNX1 mutations in germline cells may cause familial platelet disorder (FPD), an inherited bone marrow failure syndrome (IBMFS) associated with an increased lifetime risk of AML." (PMID 35765406, 2022).
breast invasive carcinoma (5 papers, 2014 to 2022). "For RUNX1, mutation ranked first in all alternate types in breast invasive lobular carcinoma (8.02%), followed by breast invasive carcinoma NOS (4.11%), and breast invasive ductal carcinoma (3.10%)." (PMID 34485309, 2021). "The expression levels of RUNX1 varied significantly in Breast invasive carcinoma(BRCA), KIRC, PAAD, THCA, and UCEC (all P < 0.05)." (PMID 35534796, 2022). "We have now addressed this need and show that 366/483 (76%) of invasive breast carcinomas in a tumour tissue microarray were positive for RUNX1 protein." (PMID 24967588, 2014). "The subtypes with the highest frequency of all alternate types were breast invasive lobular carcinoma, breast invasive carcinoma NOS, and breast invasive ductal carcinoma for RUNX1, RUNX2, and RUNX3, respectively." (PMID 34485309, 2021).
congenital neutropenia (5 papers, 2016 to 2022). "Leukemic progression in severe congenital neutropenia was used as a disease model to evaluate the clinical, molecular, and mechanistic basis of RUNX1 mutations identified in hematological malignancies." (PMID 35765406, 2022). "show that acquisition of a mutation in Cxxc4 results in increased CXXC4 protein levels, reduced TET2 protein, increased inflammatory signaling, and leukemic progression of a CSF3R/RUNX1 mutant mouse model of severe congenital neutropenia (SCN)." (PMID 33205068, 2020). "The final diagnosis became SAA and congenital neutropenia in two patients, in whom the expression of the RUNX1 gene (and possibly other uninvestigated genes) was reduced: both these conditions are usually not hereditary." (PMID 29344089, 2018).
disc degeneration (5 papers, 2020 to 2024). "Furthermore, RUNX1 enhances coccygeal disc hydration content while mitigating disc degeneration by minimizing loss of disc cartilage and other constituents." (PMID 39543114, 2024). "Compared to the control group, administration of RUNX1 mRNA nanomicelles significantly maintained a higher disc height in rats with coccygeal disc degeneration and prevented fibrosis of the disc tissue." (PMID 39543114, 2024). "Nevertheless, the role of Runx1 in the progression and pathogenesis of disc degeneration is controversial, with limited information available." (PMID 35008997, 2022). "Further studies using in vitro cell culture and valid in vivo animal models were needed to validate our findings and mechanistically support the role of RUNX1 in experimental models of disc degeneration." (PMID 32659941, 2020). "Polyplex Nanomicelles (PNM) efficiently deliver Runx1 mRNA to primary BMSCs and are shown to play a role in alleviating the progress of vertebral disc degenerative disease after injection of PNM-Runx1 to rat disc degeneration model." (PMID 36434667, 2022).
esophageal squamous cell carcinoma (5 papers, 2021 to 2025). Esophageal squamous cell carcinoma (ESCC) is a type of esophageal carcinoma (EC) that can affect any part of the esophagus, but is usually located in the upper or middle third. "LncRNA-uc002yug. can promote the binding of RUNX1 to an alternative splicing factor, leading to the production of more RUNX1a, thus promoting the progression of esophageal squamous cell carcinoma (ESCC)." (PMID 36429115, 2022).
head and neck cancer (5 papers, 2020 to 2023). A primary or metastatic malignant neoplasm affecting the head and neck. "RUNX1 has been reported to be a driver in cancer types and a member of the Runt family, RUNX3, has been found to have an oncogenic role in head and neck cancer." (PMID 33133131, 2020).
neurofibroma (5 papers, 2015 to 2023). An intraneural or extraneural neoplasm arising from nerve tissues and neural sheaths. "ERK phosphorylation caused by loss of NF1 increases RUNX1 activity and contributes to neurofibroma formation." (PMID 31032403, 2019). "Overall, our study supports an oncogenic role of Runx1 in neurofibroma initiation and/or maintenance, but the underlying mechanism(s) are not clear." (PMID 26697518, 2015). "Instead of chromosomal translocation and mutation frequently detected in other cancers, Runx1 is overexpressed in human and mouse neurofibroma-initiating cells, both at the messenger RNA and protein levels." (PMID 26697518, 2015). "Additional recurrent but low-frequency mutations in neurofibromas include FANCA, PTPRD, NF2, LZTR1, KNL1 and RUNX1." (PMID 37164978, 2023). "In this model, Li and colleagues confirmed that by inhibiting the expression of Runx1, the sphere number of neurofibromas reduced." (PMID 34566848, 2021). "Dual deletion of Runx1/3 genes prolonged the survival of a neurofibroma mouse model and reduced the number of neurofibroma lesions." (PMID 34359780, 2021). "By comparing gene expression between tumor-initiating cells and the remainder of tumor cells in neurofibroma, Li and colleagues found that the RUNX1 gene was highly overexpressed in human tumor initiating cells." (PMID 34359780, 2021). "We show that Pmp22 expression decreases significantly in Nf1−/− neurofibroma SCs and increases after Runx1/3 knockout or RUNX1/3-Pmp22–binding site deletion in mouse neurofibroma SCs." (PMID 31032403, 2019). "We showed that either genetic deletion or pharmacological inhibition of Runx1/3 function decreased mouse neurofibroma burden in vivo." (PMID 31032403, 2019). "We also showed that pharmacological inhibition of RUNX/CBFB activity significantly reduced mouse neurofibroma growth in vivo, implicating a novel signaling pathway involving RUNX1/3 repression of Pmp22 in neurofibroma initiation and/or maintenance." (PMID 31032403, 2019). "SOX10 expression is down-regulated in NF1−/− neurofibromas, and it is possible that RUNX1/3 binds to this TF-binding motif in our system to drive neurofibromagenesis." (PMID 31032403, 2019). "Targeted genetic deletion of RUNX1 in Schwann cells and Schwann cell progenitors delays mouse neurofibroma formation in vivo." (PMID 26697518, 2015). "Inhibition of Runx1 delayed the formation of neurofibroma in mouse models." (PMID 34359780, 2021). "Thus, we identified a signaling pathway involving RUNX1/3 suppression of Pmp22 in neurofibroma initiation and/or maintenance." (PMID 31032403, 2019). "Therefore, glial cell Runx1/3 regulates Nf1-deficient tumor cell proliferation in neurofibromas, and coactivation of Runx1/3 in SCs and/or SCPs is important for neurofibroma initiation and growth." (PMID 31032403, 2019). "We hypothesized that if Runx1/3 contributes to neurofibroma initiation, then tumor number should be reduced in Runx1fl/fl;Runx3fl/fl;Nf1fl/fl;DhhCre mice." (PMID 31032403, 2019). "With increasing knowledge of RUNX1 biology, targeting the transcription factor RUNX1 or RUNX1 pathway might provide a novel therapy for neurofibroma as well as other tumors which overexpress RUNX1." (PMID 26697518, 2015). "It is plausible that overexpression of Runx1/3 leads to low levels of PMP22 protein expression; therefore, P2 is used more to drive PMP22 protein expression in other tissues during neurofibroma formation." (PMID 31032403, 2019). "To determine whether Runx3 affects Runx1 knockout SCPs, we used shRunx3 to transduce Runx1fl/fll;Nf1fl/fl;DhhCre DRG/tumor-derived mouse neurofibroma spheres." (PMID 31032403, 2019). "This might contribute to the increase in neurofibroma nonmyelinating SCs, as compared with Runx1/3 knockout nerves in electronic micrographs (not shown)." (PMID 31032403, 2019).
neurofibroma (continued). "It is different from the Runx1 genetically conditional knockout, in which RUNX1 has no function but CBFB function is undisturbed, and the compensated Runx3 gene produces RUNX3 that can bind to CBFB to achieve RUNX transcriptional activities and contribute to neurofibroma formation." (PMID 31032403, 2019).
rectal cancer (5 papers, 2013 to 2024). A primary or metastatic malignant neoplasm that affects the rectum. "Genetic variations in RUNX1 are associated with colon and rectal cancer." (PMID 23626757, 2013). "Recent studies showed that the expression of RUNX1 was markedly up-regulated in CRC tissues and genetic variation in RUNX1 was associated with high risk for colon and rectal cancers." (PMID 28376129, 2017). "Moreover, Runx1 also has been implicated in various malignancies associated with CAF abundance, including breast, bladder, cervical, and rectal cancer, suggesting its potential involvement in other cancer types by accelerating the pathogenic MMT process for CAF formation." (PMID 37967345, 2024).
sarcoma (5 papers, 2014 to 2025). A usually aggressive malignant neoplasm of the soft tissue or bone. "Importantly, we identified the runt-related transcription factor 1 (RUNX1) and RNA-binding proteins (RBPs) fused in sarcoma (FUS) protein and recombinant ELAV-like protein 1 (ELAVL1) as mediators of circPTPN22 biogenesis." (PMID 38956466, 2024). "In addition, this study also described that the undifferentiated intimal sarcoma cells were positive for mesenchymal stem cell markers, such as RUNX-1 or CD44." (PMID 24489925, 2014). "Several of the FET-sarcoma-specific and shared transcription factors formed a protein interaction network, with MLS-specific JUN, RUNX1, FOSL2, and CREB5 as center nodes." (PMID 40988026, 2025). "Additionally, runt-related transcription factor 1 (RUNX1) negatively regulates circPTPN22 expression, while RNA-binding proteins such as FUS (fused in sarcoma) and ELAVL1 (recombinant ELAV-like protein 1) positively regulate its expression." (PMID 38956466, 2024).